CTSE (cathepsin E)
Diseases named in the same sentence as CTSE in open-access papers (continued):
Sharing a sentence is not in itself a finding about the gene and the disease.
tumor (continued). "Because tumor growth was suppressed by cathepsin E treatment in a mouse xenograft model, T11 administration might be expected to enhance therapeutic efficacy." (PMID 23365585, 2012). "We speculate that CTSE and S100P establish a delicate “balance” within the tumor microenvironment." (PMID 41301873, 2025). "In vivo, animal experiments show that CTSE knockdown inhibited peripheral blood DCP levels and tumor growth while significantly enhancing the effectiveness of anti-PD-1 immunotherapy." (PMID 40467555, 2025). "In hematological malignancies, such as follicular lymphoma, CTSE inhibits tumor growth and metastasis by cleaving TRAIL on tumor surfaces." (PMID 39736788, 2024). "CTSE overexpression was remarkably correlated with pre-CCRT and post-CCRT positive nodal status (both p < 0.001), advanced pre-CCRT and post-CCRT tumor status (p < 0.001 and p = 0.002), perineural invasion (p = 0.023), and vascular invasion (p < 0.001)." (PMID 34357018, 2021). "Further lasso regression analysis identified seven potential prognostic markers (IL27, CD1D, NCOA6, CTSE, FCGRT, CFHR1, and APOA2) of robustness, most of which are related to tumor development." (PMID 32518711, 2020). "Cathepsin E (CTSE) prevents tumor growth and metastasis by catalyzing the proteolytic release of soluble trail from tumor cell surface." (PMID 27484806, 2016). "Furthermore, we have confirmed here that the expression level of CTSE shows an increasing trend with the development of the tumor in the rat model, which suggests CTSE levels could potentially be used for the staging of PDAC and precancerous lesions in the rats." (PMID 25184278, 2014). "For pap-type GC, expressions of CTSE, MUC5AC, and MUC2 were considerably strong in both the tumor lesion and surrounding mucosa, which are quite different from the expression patterns of tub1/tub2-type GC." (PMID 23451082, 2013). "Moreover, we performed pan-cancer assays and found that LAMC2, CTSE and SLC6A14 exhibited a dysregulated level in many types of tumors, highlighting their potential function in tumor progression." (PMID 38267509, 2024). "Focusing on CRC patients with high tumor purity from the TCGA database, we found a resistant oncogenic signature of immune evasion (including REG4, CTSE, MUC1, TFF2, LCN2) that inversely correlated with cytotoxicity and immune infiltration deconvolution scores (T- and NK-cells)." (PMID 39632825, 2024). "CTSE expression of non-cancerous gastric mucosa adjacent to tumor lesion was evaluated, together with MUC5AC and MUC2." (PMID 23451082, 2013).
cancer (22 papers, 2011 to 2025). A tumor composed of atypical neoplastic, often pleomorphic cells that invade other tissues. "Since CTSE overexpression has been linked to development of many types of cancer, we wondered how specific its overexpression is to CRC." (PMID 34357018, 2021). "The results indicated that co-cultured with CTSE knockdown HepG2 or Huh7 cell lines reduced the apoptosis of cancer cells and ROS production compared to the control group." (PMID 40467555, 2025). "Gene Set Enrichment Analysis (GSEA) of DEGs in cancer cells revealed that the differential expression of CTSE was closely related to the activation of the ubiquinone signaling pathway." (PMID 40467555, 2025). "Previous studies have shown that CTSE is selectively expressed in several malignant tumors, including lung, bladder, and esophageal cancers." (PMID 41301873, 2025). "The expression of CTSE in cancer cells was significantly higher in stage III and IV patients than that in stage I and II HCC patients." (PMID 40467555, 2025). "We conducted western blot detecting CTSE expression in cancer tissues and adjacent normal tissues from 5 patients with HCC, and the results confirmed that CTSE expression in cancer tissues was significantly higher than that in adjacent normal tissues." (PMID 40467555, 2025). "It reveals the potential molecular mechanisms by which CTSE influences the generation of DCP in cancer cells by activating the ubiquinone signaling pathway." (PMID 40467555, 2025). "Collectively, our results demonstrated that CTSE can regulate the generation of abnormal prothrombin DCP in cancer cells by affecting the activity of the ubiquinone signaling pathway in HCC cells." (PMID 40467555, 2025). "Collectively, our data suggested that CTSE highly expressed cancer cells eliminate CD45+ immune cells, especially T cells, leading to a systemic immunosuppressive microenvironment." (PMID 40467555, 2025). "Here, we utilized single-cell RNA sequencing combined with spatial transcriptomics to reveal the role of cancer cell-expressed CTSE in HCC progression and immune microenvironment regulation." (PMID 40467555, 2025). "Cathepsin E (CTSE) is an intracellular aspartic protease with hydrolytic properties in immune and gastrointestinal cells, lymphoid tissues, erythrocytes, and cancer cells." (PMID 40467555, 2025). "We uncovered that CTSE high expressed cancer cells secreted more DCP through the dysregulated ubiquinone signaling pathway." (PMID 40467555, 2025). "The expression levels and proteolytic activity of CTSE can be used for early detection and diagnosis of various malignancies and have shown promising results in the development of cancer-targeted chemotherapeutic drugs." (PMID 41154834, 2025). "CTSE is an intracellular hydrolytic aspartic protease that has been found to be overexpressed in cancer tissues." (PMID 35433683, 2022). "Cathepsin E (CatE), an aspartic protease, is widely studied as an inducer of growth arrest and apoptosis in several types of cancer cells." (PMID 35181976, 2022). "We also revealed six oncogenes that have been validated to be related to the poor prognosis of patients with cancer: CTSE, CALM1, PHGDH, IL9R, and CD96." (PMID 35433683, 2022). "The latest researches showed CTSE was high expressed in various cancers, and stimulated oncogenesis and progression." (PMID 33048468, 2020). "This work presents the first demonstration of the successful integration of a novel peptide aptamer with a liquid-gated SWCNT FET to achieve highly sensitive and specific detection of Cathepsin E (CatE), a useful prognostic biomarker for cancer diagnosis." (PMID 29263412, 2017). "Using the 13 gastric, 5 colorectal, and 2 other cancer cell lines, CTSE protein production was analyzed by Western blotting." (PMID 23451082, 2013). "Cancer cells apoptosis was further confirmed by increased levels of apoptosis-related factors (caspase-3 and/or -7) that were observed in the presence of cathepsin E and its activator T11." (PMID 23365585, 2012).
cancer (continued). "The aspartic protease cathepsin E has been shown to induce apoptosis in cancer cells under physiological conditions." (PMID 21527983, 2011). "Overall, CTSE highly expressed cancer cells promote the apoptosis of Jurkat T cells." (PMID 40467555, 2025). "Although both S100P and CTSE are highly expressed in pancreatic tissue, they predict different prognostic outcomes, suggesting distinct responses to cancer treatment that may ultimately affect patient survival." (PMID 41301873, 2025). "In addition, the cell chat analysis uncovered that CTSE highly expressed cancer cells contact closely with T cells and macrophages." (PMID 40467555, 2025). "Moreover, CTSE acts as an intrinsic regulator within cancer cells, exerting cell-autonomous effects that inhibit invasion and metastasis." (PMID 41301873, 2025). "Mechanistically, CTSE highly expressed cancer cells upregulated the ubiquinone signaling pathway, enhancing the synthesis and release of des-γ-carboxy prothrombin (DCP), which subsequently activates reactive oxygen species (ROS) production and leads to apoptosis of Jurkat T cells." (PMID 40467555, 2025). "There may also be another pathway for cathepsin E-induced apoptosis of cancer cells (i.e., different target for cathepsin E than the TRAIL precursor protein)." (PMID 23365585, 2012). "Therefore, cathepsin E-activity-enhancing peptides functioning in the physiological pH range are valuable potential cancer therapeutic candidates." (PMID 21527983, 2011). "Thus, while CTSE expression within cancer cells may have inhibitory effects on invasion, its overall high tissue level correlates with a favorable prognosis." (PMID 41301873, 2025). "However, CTSE-deficient mice did neither exhibit cancer-prone phenotype nor present obvious gastric disorders." (PMID 23451082, 2013). "Thus, the activators we obtained could enhance cathepsin-E-induced cancer cell apoptosis, which indicated their potential as cancer drug precursors." (PMID 23365585, 2012). "It was previously proposed that cathepsin E cleaved off the soluble TRAIL ligand from the TRAIL precursor protein and that this ligand switched on the apoptosis pathway of cancer cells." (PMID 23365585, 2012). "Moreover, for CTSE, CXCL17, and LYZ, we explored the correlation between their expression and CLDN18.2 expression in three cancers." (PMID 39555091, 2024). "5-Aminolevulinic acid (5-ALA) (a Cathepsin E-sensitive (CTSE) PDT therapy prodrug) is a type of PS, which is designed to be activated selectively by endogenous Cathepsin E (Cath E), a proteolytic enzyme highly expressed within the cancer cells." (PMID 35778747, 2022). "Although peptide T11 could be assumed to induce cancer cell apoptosis through its activation of cathepsin E, the actual mechanism may not be so simple." (PMID 23365585, 2012).
infection (4 papers, 2015 to 2023). The state of being infected such as from the introduction of a foreign agent such as serum, vaccine, antigenic substance or organism. "The impact of this aspartic protease in the infection process has already been demonstrated in CTSE-deficient mice, which showed dramatically increased susceptibility to the bacterium Staphylococcus aureus, a bacterium, which induced autophagy in macrophages." (PMID 26226952, 2015). "This outcome suggested that CTSE expression was also partially inhibited in the early infection phase." (PMID 26226952, 2015). "The significantly reduced protein expression of CTSE at 1 h p.i. compared to 24 h p.i. suggested inhibition of this autophagy-related protease occurred in the early infection phase." (PMID 26226952, 2015). "Transcriptomic analyses and specific downregulation of protein expression with siRNAs suggested there is an association between the infection-specific over expression of BNIP3, as well as CTSE, and the autophagic activity of BMDM." (PMID 26226952, 2015). "It has been shown that mice spontaneously developing AD symptoms due to the lack of cathepsin E exhibit increased susceptibility to infection with S. aureus and Porphyromonas gingivalis." (PMID 37325619, 2023). "Additionally, the study demonstrates a relationship between the infection-specific overexpression of (BCL2/adenovirus E1B 19 kDa protein-interacting protein) BNIP3 and (cathepsin-E) CTSE and autophagy-related protein 5 (ATG5)." (PMID 37152895, 2023). "However, the infection rates of L. m.-infected BMDM significantly declined between 24 and 48 h p.i., which suggests there was a high autophagic activity accompanied by high BNIP3 and CTSE expression." (PMID 26226952, 2015).
neurological disorders (3 papers, 2023 to 2025). "Thus it is likely that CTSE may be a common molecule that is dysregulated in neurological disorders and may serve as a broad target for DPN and other neurodegenerative diseases warranting further investigations." (PMID 37462767, 2023).
digestive system tumors (1 paper, 2024). "This analysis encompassed a total of nine cathepsins include cathepsin B, cathepsin E, cathepsin F, cathepsin G, cathepsin H, cathepsin L2, cathepsin O, cathepsin S, and cathepsin Z, and six digestive system tumors (HCC, PCa, BTC, CRC, GC, and EC)." (PMID 38590662, 2024).
skin disorder (1 paper, 2020). Any deviation from the normal structure or function of the skin or subcutaneous tissue that is manifested by a characteristic set of symptoms and signs. "While several genes associated with skin disorders are specifically lost in cetaceans, CTSE is special since it is lost not only in fully aquatic cetaceans but also in terrestrial mammals." (PMID 33575564, 2020).
CTSE also shares sentences with these, for which no sentence is quoted: pancreatic ductal adenocarcinoma (3 papers); Cognitive impairment (2); neurodegenerative disease (2); acute myeloid leukemia (1); adenocarcinoma (1); adenoma (1); asthma (1); bladder transitional cell carcinoma (1); bladder tumors (1); cervical adenocarcinoma (1); cholangiocarcinoma (1); dementia with Lewy bodies (1); diabetic kidney disease (1); endometrial cancer (1); fibrosis (1); gastro-esophageal refluxate (1); head and neck squamous cell carcinoma (1); hyperplastic polyp (1); metabolic disease (1); myocardial infarction (1); nephrosclerosis (1); neuropathy (1); ovarian carcinoma (1); pancreatic diseases (1); rectal tumor (1); skin squamous cell carcinoma (1); Stroke (1); ulcerative colitis (1); vasculitis (1).